FOXO4 (forkhead box O4)
Description:
Transcription factor involved in the regulation of the insulin signaling pathway. Binds to insulin-response elements (IREs) and can activate transcription of IGFBP1. Down-regulates expression of HIF1A and suppresses hypoxia-induced transcriptional activation of HIF1A-modulated genes. Also involved in negative regulation of the cell cycle. Involved in increased proteasome activity in embryonic stem cells (ESCs) by activating expression of PSMD11 in ESCs, leading to enhanced assembly of the 26S proteasome, followed by higher proteasome activity.
Synonyms: AFX; AFX1; MLLT7
Tractability: PROTAC: UniProt records ubiquitination sites on it; ubiquitination databases record sites on it.
Gene: Protein-coding gene on chromosome X (71,095,851 to 71,103,535, forward strand). Ensembl gene ENSG00000184481.
Subcellular location: Cytoplasm; Nucleus
Subcellular location (Human Protein Atlas): Nuclear speckles; Cytosol
Pathways (Reactome):
Gene expression (Transcription): FOXO-mediated transcription of cell cycle genes; FOXO-mediated transcription of cell death genes; FOXO-mediated transcription of oxidative stress, metabolic and neuronal genes; Regulation of FOXO transcriptional activity by acetylation; Regulation of localization of FOXO transcription factors
Developmental Biology: Cardiogenesis
Disease: Constitutive Signaling by AKT1 E17K in Cancer
Metabolism of proteins: Ub-specific processing proteases
Signal Transduction: AKT phosphorylates targets in the nucleus
Gene Ontology:
Molecular function: beta-catenin binding; DNA binding; DNA-binding transcription activator activity, RNA polymerase II-specific; DNA-binding transcription factor activity; DNA-binding transcription factor binding; enzyme binding; identical protein binding; nucleic acid binding; protein binding; sequence-specific DNA binding; sequence-specific double-stranded DNA binding; DNA-binding transcription factor activity, RNA polymerase II-specific; RNA polymerase II cis-regulatory region sequence-specific DNA binding; promoter-specific chromatin binding
Biological process: insulin receptor signaling pathway; negative regulation of angiogenesis; negative regulation of cell population proliferation; negative regulation of G0 to G1 transition; negative regulation of smooth muscle cell differentiation; positive regulation of transcription by RNA polymerase II; regulation of DNA-templated transcription; response to oxidative stress; stem cell differentiation; regulation of transcription by RNA polymerase II; positive regulation of smooth muscle cell migration; response to nutrient levels; response to water-immersion restraint stress
Cellular component: cytoplasm; cytosol; nuclear speck; nucleus; chromatin; nucleoplasm
Homologues: Orthologues: chimpanzee FOXO4 (99% identical), macaque FOXO4 (99% identical), rabbit FOXO4 (92% identical), guinea pig FOXO4 (90% identical), pig FOXO4 (90% identical), mouse Foxo4 (89% identical), rat Foxo4 (88% identical), dog FOXO4 (76% identical), tropical clawed frog foxo4 (51% identical), zebrafish foxo4 (50% identical). Paralogues in human: FOXO3 (43% identical), FOXO1 (42% identical), FOXO6 (36% identical), FOXM1 (16% identical), FOXK1 (15% identical), FOXC1 (14% identical), FOXK2 (14% identical), FOXL1 (13% identical), FOXQ1 (13% identical), FOXC2 (13% identical), FOXJ2 (13% identical), FOXD1 (13% identical), and 29 more.
Diseases named in the same sentence as FOXO4 in open-access papers:
FOXO4 is named in the same sentence as 124 diseases in open-access papers, as found by Europe PMC text mining. Sharing a sentence is not in itself a finding about the gene and the disease. The quoted sentences say what the papers report.
colorectal cancer (20 papers, 2012 to 2025). A primary or metastatic malignant neoplasm that affects the colon or rectum. "For example, circRNA_103808 affected colorectal cancer cell proliferation and migration by binding to the miR-543-3p/FOXO4 axis." (PMID 35230201, 2022). "A study showed that miR-499 promoted cellular invasion and tumor metastasis in colorectal cancer by targeting FoxO4 and inhibited H2O2-induced cardiomyocyte apoptosis." (PMID 31708788, 2019). "It promotes the migration and invasion of colorectal cancer cells via regulating the expression of forkhead box O4 (FOXO4) and programmed cell death 4 (PDCD4)." (PMID 24194751, 2013). "FOXO4 was also downregulated in colorectal cancer tissues compared with normal tissues." (PMID 39085238, 2024). "Furthermore, downregulation of FOXO4 is significantly associated with low-grade lymph node metastases and stage III and IV tumors in colorectal cancer." (PMID 39085238, 2024). "Exosomal miR-128-3p overexpression could downregulate the expression of FOXO4 in colorectal cancer cells, which led to EMT." (PMID 39085238, 2024). "As a transcription factor, the FOXO4 expression was closely positively correlated with APC2 in colorectal cancer, which suggested that FOXO4 may bind the APC2 sequence and regulate its expression." (PMID 34631691, 2021). "Meanwhile, FOXO4 could promote degradation of β-catenin based on phosphorylation to inhibit the EMT process in the colorectal cancer cell." (PMID 34631691, 2021). "In 2011, Liu and colleagues found that miRNA-499-5p could promote cellular invasion and tumor metastasis in colorectal cancer by targeting FOXO4 and PDCD4 and miRNA-499-3p (3746444 A>G) was found in an invasive breast cancer cell line." (PMID 23236400, 2012). "Therefore, compared to β-catenin knockdown, Tcf-4 knockdown shows better efficacy for inhibiting proliferation and inducing apoptosis of colorectal cancer cells, which may be related to increased FOXO4 transcriptional activity." (PMID 23029137, 2012). "In short, both FOXO4 and APC2 were downregulated significantly in colorectal cancer compared with a standard control, with a positive correlation." (PMID 34631691, 2021). "We observed the effects of FOXO4 overexpression and APC2 knockdown on the migration of colorectal cancer cells by wound-healing assays." (PMID 34631691, 2021). "In vivo and in vitro experiments showed that FOXO4 inhibited EMT, migration, and in vivo metastasis of colorectal cancer cells by regulating the APC2/β-catenin axis." (PMID 34631691, 2021). "E2A, FOXO4, NFAT and MAZ play important roles in tumor cell growth and metastasis in multiple cancers, such as colorectal cancer, breast cancer, prostate cancer and lung cancer." (PMID 29348878, 2017). "TET1/FOXO4: Reduced expression levels of TET1 and FOXO4 have been identified as a prognostic indicator for colorectal cancer, indicating a negative correlation with patient outcomes." (PMID 40951343, 2025). "Similarly, in colorectal cancer (CRC), FOXO4 overexpression curtails cell migration and metastasis through reinforcement of the APC2/β‐catenin signaling axis." (PMID 41438489, 2025). "There was little previously known about FOXO4 in relation to canine OSA; however, a study investigating the role of FOXO4 in human colorectal cancer found that it had a role as a tumour suppressor, as FOXO4 was downregulated in colorectal cancers when compared to the control." (PMID 38792023, 2024). "Overexpressed FOXO4 suppressed EMT and the migration of colorectal cancer cell lines." (PMID 39085238, 2024). "Finally, we found APC2 was upregulated at the mRNA and protein levels in colorectal cancer cell lines (SW620 and HCT116) with FOXO4 overexpression (OE) for 48 h, and these similar results were verified by luciferase assay." (PMID 34631691, 2021).
gastric cancer (18 papers, 2014 to 2025). A primary or metastatic malignant neoplasm involving the stomach. "Taken together, regulation of Wnt signaling by TET1/FOXO4 is essential for metastasis-associated cellular properties, and targeting TET1/FOXO4/β-catenin pathway may serve as promising therapeutics in the prevention and treatment of gastric cancer metastasis." (PMID 35805009, 2022). "Our data suggest that loss of FOXO4 expression contributes to gastric cancer growth and metastasis, and it may serve as a potential therapeutic target for gastric cancer." (PMID 24886657, 2014). "Another study supports this claim that FOXO4 is a tumour suppressor, as it found that its expression was decreased in human gastric cancer tissue and gastric cancer cell lines." (PMID 38792023, 2024). "Next, we analyzed the expression of FOXO4, as well as the Wnt/β-catenin target and gastric cancer stem cell marker EpCAM in the human gastric cancer tissue arrays and the TCGA dataset." (PMID 35805009, 2022). "Overall, the present data show that TET1 inhibits gastric cancer metastasis, potentially by directly transactivating FOXO4 and confining β-catenin in the cytoplasm, thus reducing EMT and self-renewal of CSCs." (PMID 35805009, 2022). "Our data show that in gastric cancer FOXO4 expression can be induced by TET1, and ChIP-qPCR revealed that FOXO4 is indeed a direct TET1-demethylating target gene." (PMID 35805009, 2022). "Using gastric cancer cells, we observed that FOXO4 can directly bind to β-catenin, preventing its nuclear translocation and inhibiting its transcriptional activity." (PMID 35805009, 2022). "Recent studies have identified that FOXO4 regulated the glycolysis process of gastric cancer by disrupting the HIF-1α-FOXO4-LDHA axis." (PMID 34869590, 2021). "FOXO4 is targeted by miR-499-5p and miR-1274a for enhanced cell metastasis in colon and gastric cancers, respectively." (PMID 32372224, 2020). "FOXO4 is reported to suppress tumor proliferation and metastasis in stomach carcinoma, and its clinical significance is observed in multiple cancers." (PMID 29348878, 2017). "Collectively, FOX family paly critical roles in gastric cancer, and FOXO4 and FOXD3 were identified as independent prognostic factors for survival outcomes of gastric cancer." (PMID 27027443, 2016). "Our study give a new insight of FOXO4 gene functional role in gastric cancer and found it was an important prognostic biomarker in gastric." (PMID 27027443, 2016). "Recently study indicated that FOXO4 is down-regulated and inhibits tumor proliferation and metastasis in gastric cancer." (PMID 27027443, 2016). "Cell biological assays, subcutaneous tumorigenicity and tail vein metastatic assay in combination with lentivirus construction were performed to detect the impact of FOXO4 to gastric cancer in proliferation and metastasis in vitro and in vivo." (PMID 24886657, 2014). "The present study was aimed to investigate the expression profile of FOXO4 in gastric cancer and the effect of FOXO4 on cancer cell growth and metastasis." (PMID 24886657, 2014). "We found that the expression of FOXO4 was decreased significantly in most gastric cancer tissues and in various human gastric cancer cell lines." (PMID 24886657, 2014). "Here, we report that FOXO4 repress cell proliferation and metastasis in gastric cancer by the regulation G1 cell-cycle arrest and vimentin." (PMID 24886657, 2014). "The aim of our work has been to investigate the possible role of FOXO4 in gastric cancer carcinogenesis." (PMID 24886657, 2014). "In addition, modulation of FOXO4 expression rescues the inhibitory effects of TET1 on gastric cancer cells." (PMID 35805009, 2022). "Our data also showed that low expression of TET1 or FOXO4 predicts poor survival of gastric cancer patients, suggesting that reactivation of TET1 or FOXO4 might be a novel therapeutic approach to prevent gastric cancer metastasis." (PMID 35805009, 2022).
gastric cancer (continued). "The expression of transcription activator FOXO4 is decreased significantly in most gastric cancer tissues and in various human gastric cancer cell lines, suggesting that it may serve as a potential therapeutic target for gastric cancer." (PMID 35741813, 2022). "By co-immunoprecipitation (co-IP) assay with an anti-FOXO4 antibody, we could observe a direct interaction between FOXO4 and β-catenin in gastric cancer cells." (PMID 35805009, 2022). "Moreover, FOXO4 upregulation inhibited the metastasis of gastric cancer cells and led to significant decreases in liver and lung metastasis in vivo, whereas FOXO4 downregulation with specific siRNA promoted the metastasis of gastric cancer cells." (PMID 34123834, 2021). "In addition, FOXO4 has been shown to inhibit cervical cancer, gastric cancer, liver and nasopharyngeal cancer cell growth and tumor progression." (PMID 34692488, 2021). "In addition, it enhances chemosensitivity of resistant gastric carcinoma cells to 5-Fu by downregulating miR-642a-3p and miR-6785-5p and increasing FOXO4 expression." (PMID 34048194, 2021). "In univariate Cox proportion hazard ratio analysis, age, tumor(T) stage, Node(N) stage, metastasis(M) stage, FOXD3, FOXO4 and FOXS1 expression were significantly associated with prognosis in terms of OS of patients with gastric cancer in the TCGA cohorts (p < 0.05)." (PMID 27027443, 2016). "Up-regulating FOXO4 inhibited the growth and metastasis of gastric cancer cell lines in vitro and led to dramatic attenuation of tumor growth, and liver and lung metastasis in vivo, whereas down-regulating FOXO4 with specific siRNAs promoted the growth and metastasis of gastric cancer cell lines." (PMID 24886657, 2014). "Stringent multivariate analysis also confirmed that FOXO4, instead of TET1, is an independent prognostic factor predicting patients’ survival, suggesting that the direct regulation of Wnt signaling by FOXO4 might regulate gastric cancer progression in a more profound way than TET1." (PMID 35805009, 2022). "FOXO4 was frequently downregulated in gastric cancer and may serve as a biomarker for prognosis." (PMID 33463054, 2021). "For instance, the hypoxia-induced FOXO4/LDHA axis was found to play a pivotal role in regulating glycolysis and tumor progression in gastric cancer." (PMID 40149900, 2025). "Interestingly, knocking-down FOXO4 in TET1-overexpressing cells or overexpressing FOXO4 in TET1-knocking-down cells fully rescued the features of CSC and EMT in gastric cancer cells, suggesting that FOXO4 might be the major player downstream of TET1 to regulate metastasis-promoting Wnt signaling." (PMID 35805009, 2022). "Although FOXO4 has been shown to activate the expression of MMP-9 essential for vascular smooth muscle cell migration, it also inhibits gastric cancer cell proliferation and migration." (PMID 32372224, 2020). "In conclusion, FOX family paly critical roles in gastric cancer, and FOXO4 and FOXD3 were identified as independent prognostic factors for survival outcomes of gastric cancer." (PMID 27027443, 2016). "In the TCGA cohort, FOXO4 (HR = 0.613, 95%CI 0.452–0.832) and FOXD3 (HR = 1.704, 95%CI 1.212–2.397) were shown independently predictive of overall survival in gastric cancer after Cox proportional hazards analysis." (PMID 27027443, 2016). "Members of this family, especially FOXO4 and FOXD3, are two independent prognostic factors for OS and DFS of gastric cancer patients." (PMID 27027443, 2016). "It is the first time to report that BRD2 could promote the nucleus import of FOXO4, which again extended the functions of BRD2, making BRD2 again the potential therapeutic target of future gastric cancer chemotherapy." (PMID 39744419, 2025). "Our data also showed that low expression of TET1 or FOXO4 predicts poor survival of gastric cancer patients, suggesting reactivation of TET1 or FOXO4 might be a novel therapeutic approach to prevent gastric cancer metastasis." (PMID 35805009, 2022).
gastric cancer (continued). "Additionally, FoxO4 also plays a role in inducing downregulation of HIF1α via a VHL protein-independent mechanism, and it has been shown to directly negatively regulate HIF1α in gastric cancer cells, thereby inhibiting various responses to hypoxia." (PMID 37240290, 2023). "In conclusion, our study demonstrates a critical function of FOXO4 in the inhibition of GC proliferation and metastasis via the regulation of G1 cell-cycle arrest and EMT, suggests it may serve as a potential therapeutic target for gastric cancer." (PMID 24886657, 2014). "TET1 expression can significantly inhibit EMT and stemness properties of gastric cancer cells, while knocking-down endogenous TET1 induces metastasis and enhances self-renewal of CSCs by activating canonical Wnt signaling, which could be fully rescued by modulating FOXO4 expression." (PMID 35805009, 2022). "However, the expression and function of FOXO4 in gastric cancer were not known yet." (PMID 24886657, 2014).
breast carcinoma (13 papers, 2013 to 2024). "FOXO4 overexpression inhibits breast cancer cell growth and delays the occurrence and development of tumors in nude mice." (PMID 34692488, 2021). "Recent experimental and clinical studies have investigated that FOXO3 and FOXO4 play an important role in the progression of breast cancer, pancreatic cancer, and other cancers." (PMID 34055579, 2021). "In a parallel study, we also demonstrated that high CSN6 and low FOXO4 correlate with poor survival in breast cancer." (PMID 33101846, 2020). "Further, CSN6 reduces FOXO4 expression in breast cancer cell line." (PMID 33101846, 2020). "For example, hsa_circRNA_103809 regulates CRC proliferation and migration via miR-532-3p/FOXO4 axis; hsa_circRNA_101555 is involved in carcinogenesis of breast cancer hsa_circRNA_102619 played a suppressive role in progression of pancreatic ductal adenocarcinoma." (PMID 32221048, 2020). "The possible role of other FOXOs proteins (FOXO4 and 6) in breast cancer remains unknown." (PMID 29484124, 2018). "Moreover, in breast cancer cells, SIRT1 and FOXO4 collaborate to prevent cell apoptosis and promote tumor cell survival." (PMID 39845948, 2024). "In contrast, miR-150 over-expression promoted growth, clonogenicity and reduces apoptosis in breast cancer cells through regulating the Pro-Apoptotic Purinergic P2X7 Receptor; miR-150 promoted cellular metastasis in non-small cell lung cancer by targeting FOXO4." (PMID 30220021, 2019). "In contrast with FOXO1, FOXO3, and FOXO4, FOXO6 could therefore be an oncogene in breast cancer." (PMID 29484124, 2018).
cervical cancer (9 papers, 2015 to 2024). A primary or metastatic malignant neoplasm involving the cervix. "Down-regulation of FOXO4 not only enhances the growth and metastasis of cervical cancer, but also promotes EMT21." (PMID 38589525, 2024). "The following genes ENO1, FOSB, PA2G4, SOX9, and TEAD4 were highly expressed in cervical cancer in comparison to normal cervix (p < 0.001), while FOXO4 and MNT were significantly lower in cervical cancer (p < 0.001)." (PMID 28670312, 2017). "Taken together, our data demonstrated that elevated miR-150 targets FOXO4 expression and therefore regulates multiple genes expression, resulting in cervical cancer cell growth and survival." (PMID 26715362, 2015). "In summary, our results demonstrate the important role of elevated miR-150 in cervical cancer progression and reveal that miR-150 promotes cervical cancer cell growth and survival by targeting FOXO4." (PMID 26715362, 2015). "In contrast, miRNA-150 promotes cell growth and survival in cervical cancer by targeting FOXO4." (PMID 33848981, 2021). "The miR-150 modulates FOXO4 expression, resulting in cervical cancer cell growth and survival." (PMID 30728437, 2019). "We found that HPV E6/E7-related master regulators (ENO1, FOSB, PA2G4, SOX9, TEAD4, FOXO4, and MNT) were significantly differently expressed (p < 0.001) in the cervical cancer TCGA samples (n = 306) than in normal cervix (n = 11) tissue." (PMID 28670312, 2017).